PCARE (photoreceptor cilium actin regulator)
Description:
Plays an essential role for normal photoreceptor cell maintenance and vision.
Synonyms: C2orf71; FLJ34931; RP54
Tractability: No criterion of Open Targets' tractability assessment is met for any kind of drug.
Gene: Protein-coding gene on chromosome 2 (29,060,976 to 29,074,523, reverse strand). Ensembl gene ENSG00000179270.
Subcellular location: Cell projection, cilium, photoreceptor outer segment; Photoreceptor inner segment
Gene Ontology:
Biological process: photoreceptor cell outer segment organization; protein localization to photoreceptor outer segment
Cellular component: cilium; photoreceptor inner segment; photoreceptor outer segment
Genetic constraint (gnomAD): Loss-of-function variants: 74 observed, 86.98 expected, observed/expected ratio (o/e) 0.85, 90% interval 0.7 to 1.03. The upper end of that interval is the gene's LOEUF score, 1.03, which puts it in group 4 of 6, group 1 being the genes least tolerant of losing a copy. Missense variants: 1,768 observed, 1,645.3 expected, observed/expected ratio (o/e) 1.07, 90% interval 1.03 to 1.12. Synonymous variants: 705 observed, 659.69 expected, observed/expected ratio (o/e) 1.07, 90% interval 1 to 1.14.
Gene-disease validity (ClinGen):
ClinGen rates the evidence that PCARE causes each of these diseases.
PCARE-related retinopathy (autosomal recessive): Definitive. An inherited retinopathy caused by bi-allelic variants in the PCARE gene.
Homologues: Orthologues: chimpanzee PCARE (93% identical), macaque PCARE (92% identical), pig PCARE (65% identical), dog PCARE (65% identical), rabbit PCARE (64% identical), mouse Pcare (58% identical), rat Pcare (58% identical), guinea pig PCARE (57% identical), tropical clawed frog pcare (31% identical), zebrafish pcare2 (14% identical).
Diseases named in the same sentence as PCARE in open-access papers:
PCARE is named in the same sentence as 15 diseases in open-access papers, as found by Europe PMC text mining. Sharing a sentence is not in itself a finding about the gene and the disease. The quoted sentences say what the papers report.
retinitis pigmentosa (5 papers, 2012 to 2023). Retinitis pigmentosa (RP) is an inherited retinal dystrophy leading to progressive loss of the photoreceptors and retinal pigment epithelium and resulting in blindness usually after several decades. "PCARE is almost exclusively expressed in the retina, and mutations in PCARE are associated with inherited retinitis pigmentosa and retinal dystrophy." (PMID 34854809, 2021). "The photoreceptor cilium actin regulator PCARE, formerly known as the chromosome 2 open reading frame C2orf71 gene, was discovered for the first time when it was shown to be mutated in a subgroup of retinitis pigmentosa patients (RP54) (OMIM #613428) by homozygosity mapping." (PMID 37445847, 2023). "Photoreceptor cilium actin regulator (PCARE, previously named C2orf71) was first identified when it was shown to be mutated in a subset of retinitis pigmentosa patients (RP54)." (PMID 33392209, 2020).
Usher syndrome (5 papers, 2016 to 2025). A syndromic diseae characterized by the association of sensorineural deafness (usually congenital) with retinitis pigmentosa and progressive vision loss. "CEP250: A homozygous nonsense variant in CEP250 accompanied by a heterozygous or homozygous nonsense variant in PCARE was found to be related to an atypical Usher syndrome in a consanguineous family." (PMID 40149483, 2025).
Cone rod dystrophy (3 papers, 2014 to 2023). "Mutations in the photoreceptor-specific C2orf71 gene (also known as photoreceptor cilium actin regulator protein PCARE) cause autosomal recessive retinitis pigmentosa type 54 and cone-rod dystrophy." (PMID 37445847, 2023).
retinal degeneration (2 papers, 2018 to 2023). Degeneration of the retina. "We provide an additional excellent model organism to study retinal degeneration caused by PCARE mutations which will be useful to understand the disease mechanisms." (PMID 29946172, 2018).
retinal ciliopathies (1 paper, 2023). "In this review, we discussed C2orf71/PCARE-related human retinal ciliopathies and the respective models, focusing on their function, localization, and interactors." (PMID 37445847, 2023).
retinal disorder (2 papers, 2014 to 2023). Any disease or disorder of the retina. "Although not for PCARE, other preclinical therapies targeting retinal ciliary genes are being investigated that could shed light on a potential treatment for C2orf71 retinopathies." (PMID 37445847, 2023).
PCARE also shares sentences with these, for which no sentence is quoted: autosomal recessive retinitis pigmentosa (3 papers); Retinal dystrophy (3); Ciliopathies (2); colorectal cancer (1); developmental and epileptic encephalopathy (1); Lissencephaly (1); polycystic kidneys (1); Retinal Diseases (1); Usher syndrome type 1G (1).